INS (insulin)
Diseases named in the same sentence as INS in open-access papers (continued):
Sharing a sentence is not in itself a finding about the gene and the disease.
Insulin resistance (continued). "Ectopic fat deposition in insulin target tissues impairs the function of insulin signaling and thus impairs glucose homeostasis (i.e. induces glucose intolerance/insulin resistance)." (PMID 29666152, 2018). "Pathway-specific disturbance of insulin signaling was observed in hepatic insulin resistance in human hepatic steatosis." (PMID 29738450, 2018). "Increased level of inflammatory cytokines, such as IFN-γ, IL-1β, IL17A, IL6, and TNF-α, is also related to insulin resistance, and increased anti-inflammatory cytokines can improve glucose metabolism which regulates insulin sensitivity." (PMID 29541033, 2018). "The ratio between fasting glucose and insulin is a good measure of insulin resistance, and in humans a value below 4–5 is considered abnormal." (PMID 30597839, 2018). "With the obese cohort, insulin resistance was more evident than that in the normal weight group, in spite of the more evident two-phase insulin secretion." (PMID 29568712, 2018). "On the other hand, the observation of insulin resistance in AD forms the foundation of evaluating effects of insulin and insulin-sensitizing agents." (PMID 30541602, 2018). "Compelling evidence indicates that a defect in the insulin signaling pathway at the IRS1 level is the primary post receptor abnormality resulting in skeletal muscle insulin resistance." (PMID 29743988, 2018). "The GRK2 is also involved in inhibition of insulin signaling pathways, which results in insulin resistance." (PMID 34466413, 2018). "It has been reported that diet alone and diet and microbiota mediated epigenetic programming can affect the expression of insulin resistance and insulin signalling genes." (PMID 30213104, 2018). "Higher insulin resistance indices in the first trimester of pregnancy, as determined by the homeostasis model assessment (HOMA) utilising fasting serum glucose and insulin measures, are associated with increased risk of GDM." (PMID 29882903, 2018). "Estimated VO2 max was inversely associated with FMI, fasting insulin, HOMA‐insulin resistance (IR), HbA1c, fasting glucose, urate, CRP, triglyceride, LDL‐cholesterol, and systolic and diastolic BP, and positively associated with HDL‐cholesterol." (PMID 29411507, 2018). "The anti-insulin action of GH is very well established as liver, skeletal muscle, and adipose tissue develop insulin resistance induced by GH administration." (PMID 29487568, 2018). "Creatinine, cystatin C, lipids, fasting glucose, and insulin levels were measured, and homeostasis model assessment -insulin resistance (HOMA-IR) was calculated." (PMID 30035656, 2018). "Serum UA harbored a positive correlation with insulin secretion and insulin resistance indexes in newly diagnosed T2DM patients, which was influenced by gender, BMI, serum lipids." (PMID 29568712, 2018). "We nest sought to extend these observations from cellular models to in vivo models of insulin resistance, the HFD-induced insulin resistant mice and the leptin receptor-deficient db/db mice." (PMID 30666198, 2018). "Acute increases in plasma FFA levels can induce insulin resistance by inhibiting glucose uptake in skeletal muscle, hepatocytes, and adipocytes, and by attenuating insulin signaling in insulin receptor substrate 1 (IRS-1) -PI3K activity." (PMID 30089498, 2018). "Further, GRK2 downregulation enhances basal cardiac insulin sensitivity and ameliorates insulin resistance in an animal model of high-fat diet-induced obesity." (PMID 30147654, 2018). "Previous studies conducted in L6 muscle cells in vitro and rat muscle in vivo have indicated that increased phosphorylation levels of Ser307 and Ser636/639 of IRS-1 leads to impairment in the insulin signaling leading to insulin resistance." (PMID 30400151, 2018). "T2D is an endocrine pathological disorder characterized by two significant conditions resulting from defects in insulin secretion or reduced sensitivity of the tissue to insulin (insulin resistance) and pancreas β-cells dysfunction." (PMID 29769061, 2018).
Insulin resistance (continued). "We cannot exclude the possibility that MAPK upregulation or blockage of lipid deposition by AMPK activator prevents fatty acid-induced insulin resistance by directly targeting proximal components of the insulin signaling cascade." (PMID 29713651, 2018). "Insulin requirement rate was higher in ART-GDM group possibly due to higher insulin resistance in ART-GDM group." (PMID 30547777, 2018). "Resveratrol enhances insulin-stimulated glucose uptake in cultured cells and, in vivo, reduces glycemia, insulinemia, and improves insulin resistance in diet-induced insulin-resistant mice." (PMID 30400297, 2018). "Insulin resistance denotes declined insulin sensitivity in insulin targeted cells or tissues, while insufficient insulin secretion is related to pancreatic β-cell dysfunction and the loss of β-cell mass." (PMID 30598071, 2018). "Our earlier studies also showed that substitution of linoleic acid with ALA (n-6:n-3 ratio of 2) or LC n-3 PUFA (n-6:n-3 ratio of 5) prevented sucrose induced insulin resistance by increasing peripheral insulin sensitivity." (PMID 30026586, 2018). "Indirectly, miRNAs have been identified as modulators of inflammation-derived insulin resistance, by controlling/tuning the activity of innate immune cells in insulin target tissues." (PMID 30469501, 2018). "Studies have shown that serine phosphorylation of IRS-1 leads to impairment in the insulin-signaling pathway and contributes to insulin resistance." (PMID 30400151, 2018). "When it comes to yogurts, their frequent consumption, for example amongst American children, is associated with better diet quality, lower levels of fasting insulin, reduced insulin resistance scores and improved insulin sensitivity scores." (PMID 30072658, 2018). "Metabolic characteristics indicate that GDM women have significantly increased fasting glucose, 1-h and 2-h insulin levels in the presence of insulin resistance (as indicated by significantly reduced insulin sensitivity values)." (PMID 29358694, 2018). "MiR-29 inhibits the insulin-stimulated glucose uptake, and promotes insulin resistance, resulting in the development of T2D." (PMID 30445764, 2018). "Under high-fat diet feeding, loss of CMKLR1 exacerbates the glucose intolerance, increases insulin level and enhances insulin resistance in mice." (PMID 29848608, 2018). "A relationship between the AGT gene, AGT levels, and insulin sensitivity in humans has been suggested with an association between AGT M235T polymorphism and increased insulin resistance." (PMID 29484134, 2018). "4-Hydroxyisoleucine stimulates glucose-dependent insulin secretion, reduces insulin resistance and inhibits sucrose α-d-glucosidase and α-amylase." (PMID 29300317, 2018). "The relationship between insulin resistance and insulin secretion follows a clear hyperbola, and as long as the insulin secretory capacity is sufficient, the glucose homeostasis would be predicted to remain steady, and prevent the development of GDM." (PMID 30360536, 2018). "Leptin is known to induce insulin resistance, hepatic steatosis and has proinflammatory role and also contributes to fibrosis, whereas, adiponectin has anti-inflammatory and insulin sensitizing effect." (PMID 30026586, 2018). "Insulin resistance results in hyperinsulinemia due to insufficiency of insulin action on glucose uptake in skeletal muscles and fatty tissues." (PMID 30347717, 2018). "Over time, however, insulin resistance can lead to type 2 diabetes and prediabetes, because the β cells fail to keep up with the body’s increased need for insulin." (PMID 29799467, 2018). "The insulin resistance occurs when there are problems in transduction of the insulin-induced signal, generating failings in translocation pathway of GLUT4 that remain in vesicles into the cytoplasm." (PMID 29971166, 2018). "Ezetimibe is able to improve insulin resistance, particularly in patients with MS and seems to be more potent in insulin-resistant patients." (PMID 29593789, 2018).
Insulin resistance (continued). "Chronic insulin resistance leads to hyperinsulinemia and resulting inactivation of insulin signaling pathways." (PMID 30400826, 2018). "In T2DM pancreatic beta cells produce insufficient amounts of insulin to maintain normoglycemia or produce excessive amounts due to failure in the peripheral tissues insulin response, which generates insulin resistance." (PMID 29924854, 2018). "This hepatic insulin resistance leads to the overproduction of glucose and stimulation of insulin secretion." (PMID 30310390, 2018). "Brain insulin resistance and subsequent impairment of insulin and insulin-like growth factor (IGF) signaling are associated with the neurodegenerative and clinical features of AD." (PMID 30061810, 2018). "CC can effectively regulate blood lipid metabolism, improve glucose tolerance, reduce insulin resistance, improve insulin sensitivity, reduce serum inflammatory cytokines, and alleviate lipid peroxidation." (PMID 30302116, 2018). "The HFD fed rats had increased epididymal fat pad weight and higher basal insulin levels indicating the development of insulin resistance." (PMID 30228369, 2018). "The non-significant association between IL-6 and DI after adjustment for change in insulin sensitivity is consistent with prior reports that IL-6 contributes to the development of insulin resistance." (PMID 30102726, 2018). "Decreased insulin sensitivity and insulin resistance had already been reported in the MS rats that received the same treatment as our LTS group by using the euglycemic clamp technique." (PMID 29882756, 2018). "Among those patients, a significant reduction of levels of AST, ALT, and insulin and in insulin resistance (expressed by the HOMA-IR index) was observed." (PMID 30631760, 2018). "Gestational diabetes is believed to develop in women whose insulin production is insufficient to counteract increasing insulin resistance, although some metabolic heterogeneity has been described when comparing women with gestational diabetes to controls." (PMID 30424584, 2018). "Hepatic insulin resistance was assessed by comparing expression of insulin-regulated genes following an oral glucose load,that increased plasma insulin levels, with the expression observed in the feed-deprived state." (PMID 31061673, 2018). "In skeletal muscle, the major causes of insulin resistance are thought to be the excess accumulation of intramyocellular lipid (IMCL) and the inhibition of one or several steps in the insulin signaling cascade." (PMID 29747466, 2018). "Our integrated analysis of insulin-resistant proteomes from in vivo and in vitro models, and human, pointed toward a convergence upon dysregulated CoQ biosynthesis in insulin resistance." (PMID 29402381, 2018). "Treatment of HepG2 cells with HG for 24 h induced insulin resistance, as demonstrated by an impairment of insulin-stimulated Akt phosphorylation." (PMID 29709004, 2018). "Other authors showed the beneficial effects of A. melanocarpa extract on attenuating insulin resistance and improving insulin sensitivity in HFd-induced obese mice." (PMID 30577476, 2018). "In contrast, PA has a fundamental role in reducing muscle insulin resistance and normalizing circulating insulin levels." (PMID 30363988, 2018). "MitoPQ caused a specific defect in insulin regulation of GLUT4 trafficking, and other actions of insulin remained intact, as has been observed in other models of insulin resistance." (PMID 29599292, 2018). "ER stress-induced insulin resistance stems in part from the disruption of insulin signaling in insulin-responsive cells." (PMID 29921793, 2018). "The improvement in glucose tolerance and insulin sensitivity in TG9 mice correlated with a ~60% decrease in insulin resistance markers retinol-binding protein 4 (RBP4) and resistin in epidydimal fat pads isolated from ritonavir-treated animals." (PMID 29691457, 2018).
Insulin resistance (continued). "Insulin resistance occurs when an individual's cells become insensitive to insulin's message to absorb glucose from the bloodstream." (PMID 30538987, 2018). "Insulin resistance is defined as the inability of insulin to properly stimulate glucose uptake in skeletal muscle and adipose tissue and to inhibit hepatic glucose production." (PMID 30116154, 2018). "These girls present increased fat mass, abdominal fat deposits, insulin resistance and increased plasma concentrations of insulin and leptin." (PMID 29914129, 2018). "In the present study, hypertension and insulin resistance (low insulin sensitivity) were frequently observed in the obese group." (PMID 30035656, 2018). "The first condition should mimic increased fasting glycaemia and insulin resistance, the second condition impaired insulin secretion in a severely diabetic pregnant woman." (PMID 29358694, 2018). "Insulin resistance can promote the development of atherosclerosis through increased glucose and insulin concentrations and also mechanisms that involve dyslipidemia, hypertension, and inflammation." (PMID 29732028, 2018). "Insulin resistance occurs when cells are incapable of efficiently responding to a normal dose of insulin." (PMID 30574122, 2018). "Insulin and inflammatory signaling pathway have close cross talks which turned out to insulin resistance in PCOS." (PMID 29615083, 2018). "Insulin, glucose, homeostasis model assessment insulin resistance and triglyceride (− 2.9 ± 4.1 μIU/ml, p < 0.05; − 10.9 ± 16.9 mg/dl, p < 0.05; − 0.9 ± 1.3, p < 0.05; − 43.8 ± 41.9 mg/dl, p < 0.01) decreased in the exercise plus ADCR group only." (PMID 30219052, 2018). "IL-1β is a ligand for the IL-1 receptor which, like TLR4, signals via MyD88, IL-1 receptor-activated kinases (IRAK1 to 4), IKK, and NF-κB and should thus potentiate the whole model for insulin resistance in insulin target cells." (PMID 30116482, 2018). "To confirm the ameliorative effect of GN on insulin resistance, we examined insulin signaling in 2-AG-treated HepG2 cells." (PMID 29570673, 2018). "In contrast, Hsp72-deficient mice exhibit obesity and insulin resistance, suggesting that HSP72 enhances muscle insulin sensitivity by promoting fatty acid oxidation and reducing fat storage and adiposity in skeletal muscle via the HSP72-Parkin axis." (PMID 30307158, 2018). "In IPGTT, ITT and IPTT analysis, insulin treatment largely attenuated insulin resistance and promoted hepatic GNG in sepsis rats." (PMID 29285858, 2018). "Metformin treatment ameliorated systemic insulin resistance and augmented the hepatic insulin signaling cascade." (PMID 29739997, 2018). "The deletion of S6K1 is sufficient to improve insulin sensitivity in mice and in fat-fed rodents, while the activated mTOR pathway leads to an impaired insulin signaling and insulin resistance." (PMID 30034573, 2018). "In the present study we used HOMA-IR as a marker insulin resistance but our results are also supported by studies investigating the effects of intranasal insulin administration on brain reward signalling." (PMID 30445718, 2018). "Insulin resistance arises due to decreased insulin sensitivity of muscle, liver, and fat cells to insulin." (PMID 29950970, 2018). "Insulin resistance, primarily in liver, muscle and adipose tissue as well, spoils glucose disposal, leading to β-cell insulin increase and hyperinsulinemia in a compensatory manner." (PMID 30559718, 2018). "As BLEx treatment restored the 2-NBDG uptake under TNF-α treatment, BLEx is a promising material that is capable of promoting insulin signaling and alleviating insulin resistance." (PMID 29872751, 2018). "This raises interest in the pathways that regulate insulin sensitivity of podocytes and specifically in the perturbations in these pathways leading to the development of insulin resistance of these specialized cells." (PMID 29686650, 2018).
Insulin resistance (continued). "This is because fructose-induced insulin resistance and hyperinsulinaemia in normal rats are complemented by pancreatic β-cells dysfunction that impedes insulin production." (PMID 29769061, 2018). "The overexpression of hIAPP in transgenic mice shows that these amyloids induce the same metabolic phenotype as those in type 2 diabetes: impaired insulin secretion, insulin resistance, and hyperglycemia." (PMID 29921793, 2018). "JPP treatment reduced to control levels the insulin resistance and improved insulin sensitivity only at the lowest dose (JPP-I; p < 0.05)." (PMID 30186630, 2018). "Insulin resistance (IR) is a pathological state in which cells don’t respond to the normal physiological dose of insulin." (PMID 30572687, 2018). "Insulin sensitivity, as assessed by homeostatic model assessment-insulin resistance (HOMA-IR), was also unaltered." (PMID 30326639, 2018). "There are evidences that show a link between decreased Mg2+ concentration and reduction of tyrosine-kinase activity at the IR level, which results in the impairment of insulin action and development of insulin resistance." (PMID 29891771, 2018). "PKCε activation participates in the pathogenesis of lipid-induced insulin resistance through defecting insulin-stimulated IRS-2 tyrosine phosphorylation." (PMID 29700319, 2018). "HCV infection is positively associated with the homeostasis model assessment-insulin resistance (HOMA-IR) index in humans, probably due to impairment of insulin signaling in hepatocytes." (PMID 29411291, 2018). "Pregnancy can induce significant insulin resistance in women with pre-disposing factors and, coupled with an insufficient compensatory insulin secretory response, maternal hyperglycaemia ensues." (PMID 29882903, 2018). "For example, insulin levels in patients afflicted by T2D range from very low (due to pancreatic beta cell failure to produce insulin) to higher than normal levels (due to insulin resistance)." (PMID 28550272, 2018). "Steady-state insulin assessment model (HOMA-IR) can reflect the degree of whole body insulin resistance during fasting." (PMID 30373519, 2018). "Such an interrelationship indeed exists, but two-thirds of the individual variation of insulin resistance cannot be explained by fasting insulin levels." (PMID 30541568, 2018). "IL-6 induced insulin resistance and insulin secretion dysfunction by promoting lipid oxidation and participates in promoting the occurrence and development of DN." (PMID 30210570, 2018). "Insulin resistance is an impairment of insulin-mediated suppression of gluconeogenesis in the liver and of insulin-mediated promotion of glucose uptake in the adipose tissue and skeletal muscle." (PMID 29718998, 2018). "In reviewing the studies on the effects of exercise on myonectin and insulin resistance, contradictory results were observed; in some cases, myonectin and insulin resistance increased and in some others, they decreased." (PMID 30894898, 2018). "Insulin resistance in vascular endothelium promotes hypertension, atherosclerosis, and disrupts systemic insulin sensitivity and glucose homeostasis." (PMID 30142166, 2018). "The results from the MIRKO mice suggest that impaired insulin signaling in MΦs improved obesity-induced inflammation and insulin resistance." (PMID 30451856, 2018). "In fact, hepatic steatosis impairs the hepatic insulin signaling and accelerates the development of insulin resistance." (PMID 30081580, 2018). "Type 2 diabetes is characterized by insufficient insulin production or insulin resistance which leads to glucose metabolism disorders such as chronic hyperglycemia and dyslipidaemia." (PMID 29751685, 2018). "Exhaustion of islets would lead to inability to secrete sufficient insulin to compensate insulin resistance and would trigger the development of T2DM." (PMID 30134843, 2018).